ACE (angiotensin I converting enzyme)
Diseases named in the same sentence as ACE in open-access papers (continued):
Sharing a sentence is not in itself a finding about the gene and the disease.
tumor (continued). "In general, healthy ECs and tumor-derived ECs were positive for all tested markers except for CD34 (VWF+, ACE+, CD31+, CD133+, CD105+), but pathological ECs were characterized by lower levels of expression." (PMID 34445568, 2021). "In most tumors, ACE and AGTR1 (in the classical axis) possessed a closer correlation with non-tumor components than those members in the alternative axis and AGTR2." (PMID 34671200, 2021). "A detailed biochemical understanding of how ACE activates myeloid cells and which ACE peptide(s) (substrate or product) mediate these effects could lead to the development of novel therapies for boosting immunity against a variety of stimuli, including bacterial infection and tumor." (PMID 32508938, 2020). "They conducted a prospective study and collected serum levels of four tumour markers including NSE, cancer antigen 125 (CA125), ACE and CYFRA21-1 before anti-TB chemotherapy in 40 male TB patients (during 2005–2007)." (PMID 31642468, 2019). "We indeed utilized these vascular mediators (e.g., NO generators and ACE inhibitors) to augment the EPR effect and thus enhance the delivery of nanodrugs to tumor tissues." (PMID 31315251, 2019). "This ESC-like population expresses components of the renin-angiotensin system (RAS): pro(renin) receptor (PRR), angiotensin converting enzyme (ACE), angiotensin II receptor 1 (ATIIR1), and angiotensin II receptor 2 (ATIIR2) in the microvessels in this tumor." (PMID 30949483, 2019). "This highest sensitivity was superior to those of other tumour markers: 55.55% for CA125, 28.94% for ACE and 7.6% for CYFRA21-1." (PMID 31642468, 2019). "There is evidence showing that that both ACE inhibition and AGTR1 blockade inhibit tumor angiogenesis, vascular density, tumor growth, reduced tumor volume, cell proliferation, and mitotic index and they actually reduce metastasis, too." (PMID 31554351, 2019). "Recent studies showed that ACE inhibitors or ARBs effectively inhibited NSCLC cell proliferation and lung tumor metastases to prevent distal metastasis of the tumor." (PMID 31133857, 2019). "Recent investigations into the RAS in IH demonstrate the presence of ACE and ATIIR2 on the hemogenic endothelium of this tumor, and the proliferative effect of ATII via ATIIR2 on IH-derived cells." (PMID 31024924, 2019). "Tumor markers such as; alpha-feto protein, beta-chorionic gonadotrophic hormone, CA125, CA19-9 and ACE; were measured in three patients (33%) and were normal as well as the hormones (estradiol, inhibin)." (PMID 31447979, 2018). "PRR, ATIIR1, and ATIIR2 are localized to the CSC subpopulations within the tumor nests and the peritumoral stroma, while PRR and ACE are localized to the endothelium of the microvessels within the peritumoral stroma." (PMID 28626726, 2017). "Soluble interleukin 2-receptor (sIL2-R), angiotensin-converting enzyme (ACE), antinuclear antibody, anti-neutrophil cytoplasmic antibody (ANCA), and tumor markers were all within normal limits." (PMID 27245327, 2016). "Numerous studies have demonstrated that ACE is involved in angiogenesis and VEGF expression in different tumor lines." (PMID 25401104, 2014). "ACE, AT1R, MasR, and angiotensinogen were differentially expressed in control CRC liver metastases compared to the naïve (non-tumor bearing) and the tumor-bearing liver." (PMID 20380732, 2010). "Key components of the RAS, namely angiotensinogen, ACE, ACE2, AT1R, AT2R, and the MasR were expressed in the sham liver, tumor-induced liver, and in CRC liver metastases (tumors) at all stages examined." (PMID 20380732, 2010). "Numerous studies have demonstrated that ACE inhibitors (known to block Ang II formation) decrease cellular proliferation, angiogenesis, and VEGF expression in different tumor cell lines." (PMID 20431722, 2010).
tumor (continued). "Previous studies showed that the angiotensin II–AT1R system is deeply involved in tumour growth, metastasis and angiogenesis in experimental animal models, suggesting a therapeutic potential of RAS blockade using an ACE inhibitor or AT1R blocker." (PMID 16434990, 2006). "In the tumour-related RAS, angiotensin II is abundantly generated from angiotensin I by angiotensin-converting enzyme (ACE), and AT1R expression is generally upregulated." (PMID 16434990, 2006). "Notably, ACE appears to act as a detrimental factor in LUSC (p = 0.05, HR = 1.14, 95%CI (1.00, 1.30), potentially exacerbating tumor progression, whereas in LUAD, it tends to play a protective role (p = 0.39)." (PMID 41490177, 2026). "Thus, we could hypothesize that ACE inhibitors exert an antiangiogenic activity that hinders the extravasation of CTCs and/or the formation of a metastatic colony in distant organs; alternatively, they could induce tumor mass dormancy or prolong dormancy maintenance." (PMID 37065865, 2023). "In normal ovary, in postmenopausal women, ACE activity was found significantly higher and in an OC xenograft model the inhibition the Angiotensin II, a RAS component, blocked the formation of the tumor spheroids and metastastases in EGFR-dependent manner." (PMID 37041632, 2023). "More recently, researchers have suggested that ACE inhibitors have no direct cytotoxicity against tumor cells but rather show the potential to inhibit tumor growth owing to the suppression of vascular endothelial growth factor-induced angiogenesis in vivo." (PMID 37065865, 2023). "The effects on stability and AsPC-1 tumor uptake were assessed in mice without or during NEP/ACE inhibition." (PMID 37958525, 2023). "Conversely, another study that investigated the impact of ACE inhibitors in the setting of preoperative treatment reported no immediate effects on tumor response but did find an improvement in relapse-free survival." (PMID 37065865, 2023). "ACE gene expression was marginally significantly reduced in the CRC tumor samples, i.e., it was significant on its own, but not with the multiple comparison correction." (PMID 34285715, 2021). "It is worth to mention that the TCGA tumor samples were taken before any chemotherapy, thus, no induction of ACE expression by bleomycin." (PMID 33858332, 2021). "ACE was present on the endothelium of normal vessels in all samples but was not present within the tumor in all 15 samples." (PMID 33916968, 2021). "ACE (red) was localized to the CD31+ (green) endothelium of the tumor microvessels within the PTS." (PMID 33513805, 2021). "The results showed that ACE treatment could significantly reduce both the protein and mRNA expression levels of SDF-1 and CXCR4 in tumour tissues." (PMID 34531745, 2021). "Detection of ACE by WB and RT-qPCR likely reflects the normal vasculature as seen in immunohistochemical staining, rather than expression by the tumor itself." (PMID 33916968, 2021). "It summarized that different angiotensin I-converting enzyme genotypes and AT1 receptors blockade with an ARB stimulate tumor angiogenesis might be related to different carcinogenesis results after ACEi/ARB treatment." (PMID 34763668, 2021). "The treatment with captopril (inhibitor of ACE) in CRC metastases resulted in a decrease in LM volume and downregulation of ATG and AT1R expression, with increased ACE expression in the final stages of tumor growth." (PMID 32429087, 2020). "In CRC, tumor MPs such as MUC1-, ACE- and CA19-9 bearing MPs, were significantly less observed in case of thrombo embolic event (0, 0 and 0 MPs/ μL respectively) than without (15 [0–6673] MPs/ μL, p=0.02; 20 [0–1850] MPs/ μL, p=0.002; and 21 [0–4337] MPs/ μL, p=0.0009, respectively)." (PMID 29228619, 2017). "In summary, our study found that local Ang II predominantly exists in a hypoxic tumor microenvironment, in which tumor cells autocrinely produce Ang II through a chymase-dependent rather than an ACE-dependent mechanism." (PMID 28205588, 2017).
tumor (continued). "–(Pro)renin receptor (PRR), angiotensin II receptor 1, and angiotensin II receptor 2 are localized to the CSC subpopulations within the tumor nests and the peritumoral stroma, while PRR and ACE are localized to the endothelium of the microvessels within the peritumoral stroma." (PMID 28626726, 2017). "Beyond the tumor immune microenvironment, the AngII/AT1R axis is also crucial for the maturation and function of immunostimulatory myeloid cells, and ACE overexpression in monocytic cells enhances antitumor immunity, although the latter effect seems to be independent of the AngII/AT1R axis." (PMID 28978752, 2017). "ACE (green, arrows) was expressed on the endothelium of the microvessels within the peri-tumoral stroma, which expressed SOX2 (red), distinct from the tumor nests." (PMID 27730124, 2016). "It should be stressed that the impact of in situ ACE inhibition on the bioavailability and tumor localization of [111In-DOTA]MG11 in vivo has not been thus far investigated." (PMID 26882895, 2016). "Treatment with the ACE inhibitor, enalapril, counteracted UVB-induced wrinkles and skin damage." (PMID 25772062, 2015). "Furthermore, ACE inhibitors downregulate matrix metalloproteinases, MMP-2, and MMP-9 and inhibit tumor metastasis." (PMID 24223058, 2013). "The RAS is now known to contribute to the regulation of tumour growth in several types of malignancy, but to date most research has focused on the inhibitory potential of blocking the classical RAS pathway, namely AT1R blockade or ACE inhibition." (PMID 20584290, 2010). "The high levels of tumor-derived ACE described here support reports of an up-regulation of ACE mRNA in primary CRCs compared to corresponding nonlesional tissues." (PMID 20380732, 2010). "This modification led to significantly better in vivo stability vs. the [99mTc]Tc-DT1 parent, especially in terms of resistance to ACE, whilst other important biological traits, such as receptor affinity, cell internalization, good tumor targeting, and pharmacokinetics were not negatively affected." (PMID 40142972, 2025). "Furthermore, [99mTc]Tc-DT9 achieved the highest cell internalization and tumor uptake even without NEP/ACE-inhibition but with unfavorably high background radioactivity levels." (PMID 37631306, 2023). "The impact of these modifications on receptor affinity and internalization was studied in NTS1R-positive cells, whereas the effects on metabolic stability and AsPC-1 tumor uptake were assessed in mice without or during NEP/ACE inhibition in comparison with the unmodified [99mTc]Tc-DT1 reference." (PMID 37958525, 2023). "However, treatment with ACE inhibitors (ACEi) or AT1 antagonists (ARBs) does not seem to be very effective in inhibiting tumor growth." (PMID 35409002, 2022). "We showed that the expression of proteins specific to ECs (ACE+, VWF+), their differentiation (CD31+, CD 133+, CD105+, CD34-), their adhesion properties (ICAM-1+, VCAM-1+, CD62-L+), and their barrier formation (ZO-1+) were all downregulated in tumor-derived ECs." (PMID 34445568, 2021). "Interestingly, in this study, we found that Ang II generation in hypoxic tumor cells was independent of ACE expression." (PMID 28205588, 2017). "Taking these results into account, we hypothesize that the higher ACE expression in tumor vessels and the lower APA expression in CCRCC tumor cells could lead to an accumulation of Ang II in tumor microenvironment, thereby stimulating angiogenesis and promoting tumor growth and invasiveness." (PMID 28809959, 2017). "Interestingly, ACE was not expressed in tumor cells but rather in endothelial cells, suggesting that the source of ACE activity was the tumor vasculature." (PMID 28809959, 2017).
tumor (continued). "In contrast, coinjection of the ACE inhibitor Lis did not provoke any raise in tumor values (1.80 ± 0.74 % ID/g) vs. controls (P > 0.05), whereas coinjection of both peptidase inhibitors PA and Lis did not provoke any additional increase in the PA group values (14.51 ± 4.73 % ID/g, P > 0.05)." (PMID 26882895, 2016). "The tumor showed positive immunoreactivity for ACE and negative to anti-PS-100." (PMID 24282649, 2013). "Although the role of angiotensin II in VEGF-mediated tumour development has not yet been elucidated, an ACE inhibitor significantly attenuated VEGF-mediated tumour development, accompanying the suppression of neovascularisation in the tumour and VEGF-induced endothelial cell migration." (PMID 15813980, 2004). "Hence, it is tempting to speculate that the anti-tumor properties of ACE inhibitors might not be exclusively mediated by impairment of the renin-angiotensin system axis, but in fact may also involve the kallikrein-kinin system axis." (PMID 23691222, 2013). "Both ACE and HSPB8 showed significant negative correlations with mRNAsi, indicating involvement in tumor cell differentiation, growth rate, and invasiveness modulation, underscoring their potential as therapeutic targets in LUSC." (PMID 41490177, 2026). "The protein levels of P(RR) and the mRNA levels of P(RR), AGTR, ACE, and ACE2 in tumor tissues were considerably higher than in the surrounding normal tissue." (PMID 37869088, 2023). "The expression of AT1R, ACE, AGT, glutamine synthetase, CD44 and Fzd7 were not significantly changed in the tumor tissues from the captopril treated mice compared to control mice (respectively)." (PMID 34073112, 2021). "ACE inhibitors reversed the beneficial effects on tumor growth, but AT1 receptor blockade did not, suggesting that the effects of ACE overexpression were not dependent of Ang II/AT1 receptor signaling." (PMID 32503281, 2020). "Other laboratory tests including a complete blood count, thyroid hormones, lipid profile, viral serologies, protein electrophoresis, purified protein derivative (PPD), angiotensin-converting enzyme (ACE) and tumor markers were without pathological findings." (PMID 25434739, 2014). "This suggests that ACE inhibitors, other than blocking the production of ANG II which subsequently binds AT1R, also generate anti-tumour effects through non-ANG II mediated pathways." (PMID 21703011, 2011). "ACE inhibitors and AT1R antagonists do not significantly impact tumor necrosis or survival in mice." (PMID 39338421, 2024). "mRNA of angiotensinogen, the precursor protein of AngII, ACE, and the AT1 receptor could be detected in HNSCC regardless of where the tumor originated." (PMID 35409002, 2022). "It should also be noted that, in a previous analysis, we observed that neither ACE nor ACE2 were expressed in RO and ChRCC, which suggests that the role of PRR in these tumours could be RAS-independent." (PMID 33578778, 2021). "Notably, ACEi reversed the beneficial effects on tumor growth, but AT1R blockade did not, suggesting that the effects of ACE overexpression were not dependent on AngII/AT1R signaling." (PMID 28978752, 2017). "Interestingly, though, the observed tumor enhancement was not statistically significant either in the case of [99mTc]Tc-DT11 during single NEP inhibition (6.14 ± 0.08% IA/g, p > 0.05) or of [99mTc]Tc-DT12 during NEP/ACE inhibition (4.48 ± 1.23% IA/g, p > 0.05)." (PMID 37958525, 2023).
infection (190 papers, 2008 to 2026). The state of being infected such as from the introduction of a foreign agent such as serum, vaccine, antigenic substance or organism. "ACE enhances ROS generation and bacterial clearance, while an ACE deficiency impairs neutrophil function, resulting in an increased infection burden." (PMID 40722848, 2025). "Possible explanations include exposure to environmental factors such as smoking, diet, and physical activity, and genetic factors associated with the mechanisms of infection by SARS-CoV-2 including the genes of the ACE/ACE2 pathways." (PMID 35250987, 2022). "Patients on vitamin D treatment and past users of ACE inhibitors were associated with higher odds of infection." (PMID 33875444, 2021). "ACEIs reduce these mediators and confer protection in experimental infection models, though they may impair antimicrobial defense, as evidenced by reduced neutrophil function and an increased bacterial load in ACE-deficient mice." (PMID 40722848, 2025). "Importantly, ACE inhibition abrogates these protective effects, raising concerns regarding its impact on the perioperative infection risk." (PMID 40722848, 2025). "Furthermore, large observational studies and meta-analyses generally show no major effect on severe outcomes or mortality in hypertensive patients using ACE inhibitors, supporting their continued use despite the slight infection risk." (PMID 40247607, 2025). "Finally, treatment with the antihypertensive ACE inhibitor, lisinopril, showed negligible impact on receptor expression or susceptibility of renal cells to infection." (PMID 38334329, 2024). "Therefore, the ACE D/I polymorphism can play a role in the spread of COVID-19 and in the outcome of the infection, especially in European populations." (PMID 32899935, 2020). "Some authors, in agreement with the role of ACE in lung infections caused by SARS-CoV-2, have suggested how the ACE D/I genotype may influence the clinical course of the infection." (PMID 32899935, 2020). "We next investigated whether the ACE+ granuloma MΦ phenotype is associated with STm infection outcome in the spleens by comparing their tissue levels in WT STm and ΔsteE STm-infected mice, which have reduced bacterial persistence due to a bacterial defect in polarizing MΦ phenotypes." (PMID 36608122, 2023). "An initial suggestion that the susceptibility to infection and disease severity may be enhanced by angiotensin type-1 receptor blockers (ARBs) and ACE inhibitors (ACEIs) because they increase ACE2 levels, led to the consideration of discontinuing treatments in thousands of patients." (PMID 35203711, 2022). "In vivo and in vitro murine studies had improved bacterial clearance after L. monocytogenes and MRSA infection when ACE was overexpressed, but when ACE was deficient, mice experienced lethal infections which could be due to decreased clearance upon ACE inhibition." (PMID 36016727, 2022). "It was stated that the spike (S) proteins of coronaviruses mediate their infection through the efficient binding of the S1 domain of the SARS-CoV S protein with ACE." (PMID 36673116, 2023). "We then sought to determine the impact of ACE overexpression in myeloid cells on STm infection in vivo." (PMID 36608122, 2023). "An alteration of the ACE/ACE2 ratio, when in favor of ACE, suggests a greater probability of manifesting severe symptoms under infection due to the pro-inflammatory pathways’ enhancement." (PMID 36901403, 2023). "Functional variants that increase ACE and ACE2 gene expression were thought to cause high viral binding to membrane sites, increasing carrier susceptibility to infection." (PMID 37667339, 2023). "In the present study, SARS-CoV-2pp infection was increased by overexpression of ACE and significantly increased by coexpression of ACE2 and TMPRSS2." (PMID 36995225, 2023). "Together, these findings suggest that ACE overexpression in MΦs alone is insufficient to affect STm persistence during in vitro and in vivo infection." (PMID 36608122, 2023).